CCL3 (C-C motif chemokine ligand 3)
Diseases named in the same sentence as CCL3 in open-access papers (continued):
Sharing a sentence is not in itself a finding about the gene and the disease.
atherosclerosis (40 papers, 2012 to 2025). A disease characterized by the build-up of fatty material and calcium deposition in the arterial wall resulting in partial or complete occlusion of the arterial lumen. "However, the role of CCL3 in atherosclerosis may be dependent on the various receptors as deficiency of CCR1 in ApoE−/− mice fed a WD for 10 to 12 weeks led to accelerated atherosclerosis and greater plaque size and infiltration of T lymphocytes." (PMID 33503867, 2021). "The KGs of T cells involved in the effects of hawthorn on the PVAT microenvironment in atherosclerosis were CCL3, CCL4, MT2A, and MT1X." (PMID 40824771, 2025). "Activated platelets, neutrophils, and mast cells can release this chemokine, and neutrophils stimulated by tumor necrosis factor-alpha respond to CCL3, contributing to atherosclerosis overall by upregulating the integrins CD11b and CD18." (PMID 40535169, 2025). "Through LASSO analysis, we ultimately identified CCL3, TNF, CCR2, and CCR5 as key genes, which showed high diagnostic value in gout and atherosclerosis through ROC curve analysis." (PMID 39677038, 2024). "CCL3, a chemokine, plays a key role in recruiting monocytes and T lymphocytes to sites of inflammation in atherosclerosis." (PMID 39700090, 2024). "Inflammatory macrophage cluster identified from an atherosclerosis mouse model showed high-level expression of various genes previously assigned to a pro-atherogenic role (e.g., Ccl3, Il1b, Il1a, Nlrp3, Cebpb, Egr1, and Phlda1)." (PMID 38149246, 2023). "Differentially expressed genes CCl3, Hsap5, Mmp9, Fos, Ctsk corresponded to rheumatoid arthritis, lipid and atherosclerosis, and the Toll-like receptor signaling pathway." (PMID 36445632, 2023). "Consistent with our data, previous studies show that CCL3 and CCL5 are associated with LDL-c and atherosclerosis." (PMID 36231033, 2022). "C-C motif chemokine receptor 5 (CCR5) and its ligands CCL3 (MIP-1α), CCL4 (MIP-1β), and CCL5 (RANTES) also associate and contribute to the initiation and progression of atherosclerosis and related cardiovascular diseases." (PMID 36035865, 2022). "Absence or inhibition of CCL3 also leads to reduced neutrophil invasion and tissue protective effects in atherosclerosis, lung ischemia-reperfusion injury and focal cerebral ischemia." (PMID 33246483, 2020). "CCL3−/− mice show reduced lesion sizes and plaque formation in atherosclerosis and blockade of CCR5, using neutralizing antibodies, promotes locomotor recovery after SCI." (PMID 33246483, 2020). "To date, the CC-chemokine family has been strongly implicated in atherosclerosis with a host of CC-chemokines including MCP-1 (CCL2), RANTES (CCL5) and MIP-1α (CCL3) detected in human atherosclerotic lesions." (PMID 28282403, 2017). "Despite the known importance of chemokines in atherosclerotic lesion formation and the extensive literature on CCL2, little is known regarding the role of CCL3 in atherosclerosis or in other metabolic processes." (PMID 22359597, 2012). "Compared with chemokine receptors, the ligands CCL3, 4, and 5 seem to be better choices for biomarkers in atherosclerosis because it is possible to test their mRNA levels in circulating leukocytes." (PMID 22577254, 2012). "CCL3 and CCL4 are the inflammatory chemokines associated with atherosclerosis." (PMID 40824771, 2025). "Previous studies have reported that CCL3 may play an important role in neutrophil recruitment and the development of atherosclerosis." (PMID 37382646, 2023). "Among them, only CCR5 was related to the progression of atherosclerosis, as some of its ligands, such as CCL3, and CCL4, CCL5, could be detected in atheroma plaques." (PMID 32911750, 2020). "Indeed genetic deletion of CCR5, an important receptor for CCL3/MIP1α and CCL5/RANTES, protected atherosclerotic prone mice from atherosclerosis and appeared to be associated with impaired Th1 immunity." (PMID 23029252, 2012).
atherosclerosis (continued). "In NAFLD, CCL3 may also be involved in the infiltration of inflammatory cells in the liver, promoting liver inflammation and fibrosis, which may in turn promote the development of atherosclerosis." (PMID 39700090, 2024). "In conclusion, our study demonstrated that decreased expression of miR-24-3p and increased expression of miR-595 in patients with CAD may lead to progression of atherosclerosis plaque by regulating the expression of CCL3, CCL4, IL-1β, TNFαIP3, and NF-κBIα genes." (PMID 36381642, 2022). "Thus, CCL3 may play an important role in neutrophil recruitment and the development of atherosclerosis." (PMID 33503867, 2021). "Our results were verified by qPCR for the selected cytokines involved in immune cell activation and migration (CCL2, CCL3, CCL4, CCL5, CX3CL1), representing potential therapeutic targets in atherosclerosis." (PMID 38256102, 2024). "The expression patterns of the major migration-driving chemokines MCP-1 (CCL2), MIP-1α (CCL3), MIP-1β (CCL4), RANTES (CCL5), and fractalkine (CX3CL1) in patients with atherosclerosis were of particular interest in this study." (PMID 38256102, 2024). "In this study, through comprehensive analysis methods, four key genes—CCL3, TNF, CCR2, and CCR5—were identified, having significant impacts on the pathophysiological mechanisms of gout and atherosclerosis." (PMID 39677038, 2024). "In atherosclerosis, many studies have supported the role of the chemokine receptor CCR5 and its ligands CCL3, CCL4, and CCL5 in triggering the progression of atherosclerosis, particularly in later stages of plaque." (PMID 32346605, 2020). "In addition to CCL3, CCL4, and DUSP2, IL1B, known to be highly relevant in atherosclerosis, was highly upregulated in CM of HIV+CVD+ women." (PMID 36045343, 2022). "Additionally, increasing IL-10, IL-4, IL-13, and TGF-β and reducing IL-1β, Il-6, TNF-α, CCL3, CCL4, and CCL5 can slow the progression of atherosclerosis." (PMID 32346605, 2020). "However, evidence now supports a role for CCR5 and its ligands CCL3 (MIP-1a), CCL4 (MIP-1b), and CCL5 (RANTES) in the initiation and progression of atherosclerosis." (PMID 22577254, 2012). "Though CTA-384D8.35, CTB-114C7.4 and miR-4497 have not been studied yet, their functions could be interpreted by their target genes in the ceRNA network, including inflammatory responses (CCL3, ZFP36, IER3), apoptosis (EGR1), atherosclerosis and myocardial ischemia (FOS)." (PMID 31443660, 2019).
Stroke (40 papers, 2012 to 2025). Sudden impairment of blood flow to a part of the brain due to occlusion or rupture of an artery to the brain. "Most upregulated genes acutely after stroke were as expected early-response and inflammation associated genes such as Hspa1a, Cxcl1, Ccl3, and Fos." (PMID 37337154, 2023). "Our research excitingly revealed enhanced interactions between basophils and neutrophils via the Ccl3-Ccr1 pathway post-stroke, compared to the Sham group." (PMID 39931101, 2024). "Ccl3 appears to play a pivotal role in this progression, possibly serving as a primary therapeutic target for post-stroke treatment." (PMID 39931101, 2024). "Post‐stroke BHB therapy resulted in a substantial decrease in the expression of proinflammatory chemokines (CCL3, CXCL1, CXCL9, CXCL10), complement (C5/5a), cytokines (IFN‐γ), and myeloid cell activators (G‐CSF) in the ischemic hemisphere." (PMID 38666466, 2024). "Its ligands, CCL3/4/5, secreted by infiltrating blood‐born cells upon stroke, activate microglia and astrocytes." (PMID 37867250, 2023). "At day 6, we found the levels of CD62L and CXCL7 were equally elevated in PT and rTMS groups, while stroke-induced CCL3 expression was further promoted by rTMS." (PMID 33204331, 2020). "We also showed that during early stage of ET-1-injection stroke model expression of CCL3 is significantly upregulated at 24 and 72 h after model induction." (PMID 24324296, 2013). "Transcripts for the chemokines CCL3, CCL2 and CCL5 were increased in the ischemic hemisphere of wildtype control mice following stroke, with a peak at 12 h for CCL3 and CCL2 and a peak at 7 d for CCL5." (PMID 23301011, 2013). "This suggests potential Ccl3 involvement in post-stroke basophil cell apoptosis." (PMID 39931101, 2024). "Meanwhile, post-stroke, we posit that basophils in the front line undergo pathological alterations and, through the Ccl3-Ccr1 pathway, guide neutrophils and unaffected basophils to effect chemotactic function, participate in the removal of pathological cells and tissue repair." (PMID 39931101, 2024). "Exploring the association between obesity and cerebral inflammation after stroke, obese mice fed a high-fat (60%) diet showed larger post-stroke infarct volumes and increased chemokine expression (CXCL-1 and CCL3), blood-brain barrier (BBB) permeability, and neutrophil and microglia counts." (PMID 38992073, 2024). "Post-stroke, we posit that basophils in the front line undergo pathological alterations and, through the Ccl3-Ccr1 pathway, guide neutrophils and unaffected basophils to effect chemotactic function, participate in the removal of pathological cells and tissue repair." (PMID 39931101, 2024). "Interestingly, we observed the emergence of the Ccl3-Ccr1 pathway in basophil self-interactions after stroke." (PMID 39931101, 2024). "Levels of Ccl3 were reported to be elevated in an animal model of stroke and could recruit microglia, neutrophils, and monocytes." (PMID 37234258, 2023). "However, only let-7g* was effective in reducing the stroke-driven increases in CCL3 (p < 0.05) and CXCL1 (p < 0.005), while miR-98 attenuated the increase in IP-10 (p < 0.05) only." (PMID 32766248, 2020). "Whereas all investigated chemokines were found to be unchanged in their acute response at 12 h after stroke (TREM2-KO vs. WT), the increased expression of CCL3 and CCL2 was attenuated in TREM2-KO mice at 7 d after stroke (CCL3: to 12% ±1.3, CCL2: to 37% ±6.5, p≤0.05, n = 5/6 each)." (PMID 23301011, 2013). "The increase in brain chemokine expression (CXCL-1 and CCL3) and greater circulating blood neutrophil numbers that were observed in obese mice in the present study are likely responsible for the enhanced neutrophil infiltration into the brain in response to stroke." (PMID 26239227, 2015). "Stroke resulted in upregulated expression of adhesion molecules (P‐selectin, E‐selectin, and ICAM‐1) and chemokines (CC‐chemokine ligand (CCL)‐2, CCL‐3, CCL‐4, CCL‐5, and chemokine C‐X‐C ligand 1 (CXCL‐1))." (PMID 37122157, 2023).
Stroke (continued). "At day 22, most of the measured cytokines were slightly (CINC-1, CINC-2α/β, CINC-3, GM-CSF and VEGF) or markedly (CD54, CD62L, CXCL7, CXCL9, CXCL10, CCL3, CCL5, CCL20) induced by stroke compared to Ctl." (PMID 33204331, 2020). "We found that the expression levels of some chemokines and cytokine receptors, such as CSF1R, CSF1, CCL3, CD4, and CCR2, were significantly different in ki20227-treated stroke mice compared to vehicle-treated stroke mice." (PMID 33177990, 2020). "This prompted us to analyze in greater detail the expression levels of well-defined pro-inflammatory mediators during stroke, namely interleukin-6 (IL-6), CD68, CCL3 (MIP1α), and CCL5 (RANTES) by means of rt-PCR." (PMID 24024100, 2013). "Impressively, TXL could inhibit the stroke‐enhanced expression of adhesion molecules (P‐selectin and ICAM‐1) and chemokines (CCL‐3, CCL‐4, CCL‐5, and CXCL1)." (PMID 37122157, 2023). "Impressively, TXL could inhibit the expression of stroke‐induced upregulated adhesion molecules (P‐selectin and ICAM‐1) and chemokines (CCL‐3, CCL‐4, CCL‐5, and CXCL1)." (PMID 37122157, 2023). "Increased levels of CCL5, CCL2, CCL3, and CXCL12 found in the early phase of endothelin-1 induced stroke model were not the cause of neurodegeneration." (PMID 27635404, 2016). "We focused on such factors, i.e. IL-6, CD68, CCL3 and CCL5, which have already been described by us and others occurring in the ischemic peri-infarct area and being relevant for tMCAO-induced brain damage and post-stroke therapy." (PMID 24024100, 2013). "Indeed, TNFα, IL-1α, IL-1β, CCL2, CCL3 and CX3CR1 transcript expression differed in the ischemic cerebral tissue of TREM2-KO mice compared to littermate controls at day 7 after stroke." (PMID 23301011, 2013). "Chemokines including macrophage inflammatory protein-1α (MIP-1α or CCL3), monocyte chemotactic protein-1 (MCP-1 or CCL2) and regulated upon activation, normal T-cell expressed, and secreted (RANTES or CCL5) have shown to be released during different models of stroke." (PMID 34572077, 2021). "However, the expression of CCL2, CCL3, CCL4, CCL7, and CXCL2 was strongly increased after stroke, whereas CCL19, CCL20, and CXCL5 expression levels were not changed." (PMID 26640428, 2015). "They showed upregulation of CCL5 but not CCL2, CCL3, and CCL4 on day 0 in stroke patients." (PMID 24324296, 2013). "Although the expression of several studied chemotactic inflammatory mediators (chemokines CCL2, CCL3, CCL5, and CXCL2) was significantly increased in the early stage of this stroke model, there was no clear correlation between this expression and intensity of neurodegeneration (data not shown)." (PMID 24324296, 2013).
Arthritis (36 papers, 2005 to 2026). Inflammation of a joint. "Our research reveals that H. pylori induces the secretion of the chemokine CCL3 by macrophages, which is implicated in several inflammation-related diseases, including asthma, wound healing, arthritis, multiple sclerosis and pneumonia." (PMID 38730482, 2024). "Inhibition of osteoclast-associated CCL3 reduced osteoclast formation and function whilst attenuating arthritis-associated bone loss and controlling development of erosion in murine joints, thus uncoupling bone damage from inflammation." (PMID 30053130, 2018). "Moreover, the CCL3-null mouse arthritis model is associated with a reduction of infiltrating cells and normal appearance of the synovium and cartilage, and the absence of pannus or bone resorption, thus confirming the important role of this chemokine in OA." (PMID 27044395, 2016). "In addition, administration of a neutralizing anti-CCL2 antibody reduced ankle swelling in the rat CIA model, CCL3-deficient mice exhibited milder arthritis induced by an anti-type II collagen mAb and treatment with polyclonal anti-CCL5 antibody ameliorated adjuvant-induced arthritis in rats." (PMID 30053130, 2018). "By contrast, the mRNA expression of MCP-1 (CCL-2) and MIP-1α (CCL-3) was unchanged whatever the phase of arthritis." (PMID 35488311, 2022). "Recently, one study revealed inhibiting CCL3 can abrogate osteoclast precursor cell infusion in human osteoclast cultures and attenuate bone erosion in arthritis." (PMID 32478376, 2020). "This study focuses upon three chemokines, namely CCL5, CXCL10 and CCL3, which are potential novel therapeutic targets in arthritis." (PMID 16507178, 2006). "Our data parallel previous reports of these two chemokines in other forms of arthritis, such as RA, in which levels of CCL3 and CXCL10 measured in SF were higher than those in serum." (PMID 16507178, 2006). "This explains our finding of modest but significant elevated expression levels of IL-1, IL-6, CCL3, and MCP1 in the bone marrow cells of KLF2 heterozygous mice after induction of arthritis, which were associated with the formation of marginal erosions found in KLF2+/− mice." (PMID 31426355, 2019). "Here, we challenged the notion that CCL3 controlled joint damage in arthritis solely by its pro-inflammatory action and hypothesized osteoclast differentiation to be the primary mode of action for CCL3." (PMID 30053130, 2018). "Histological evaluation revealed a substantial reduction of leucocyte infiltration into synovial tissues, synovial hyperplasia and joint erosion by anti-CCL3 treated mice vs controls, resulting in a significantly reduced arthritis index in the wrist (P < 0.01) and elbow (P < 0.05) joint." (PMID 30053130, 2018). "In an equine IL-1β-induced carpal synovitis model, CCL2, CCL3, CCL5, and CCL11 were identified as sensitive biomarkers during the early stages of joint inflammation (synovitis), exhibiting temporal variations in their response." (PMID 40496923, 2025). "Taken together, these findings indicate that the sFasL–DR5 interaction promotes arthritis by regulating the CX3CL1–CX3CR1 axis, which increases CCL2, CCL3, and CXCL10 production by CX3CR1+ immune cells." (PMID 34223817, 2021). "The WT, Faslpr/lpr, and Fas–/– mice developed autoantibody-induced arthritis (AIA), whereas the Faslgld/gld mice exhibited attenuation of joint swelling and expression of Il6, Tnfa, Il1b, Ccl2, and Ccl3." (PMID 34223817, 2021). "We found that expression levels of IL-1β, IL-6, TNFα, CCL3 and MCP-1 molecules were significantly (p < 0.05) increased after induction of arthritis in the bone marrow of KLF2+/− mice compared to KLF2+/+ mice." (PMID 31426355, 2019). "The increased CCL3 levels and higher Ccr5 expression in LIII mice suggest that this chemokine also plays a role in early arthritis development, at least in the PIA model." (PMID 30937315, 2019).